MTOR (mechanistic target of rapamycin kinase)
Diseases named in the same sentence as MTOR in open-access papers (continued):
Sharing a sentence is not in itself a finding about the gene and the disease.
tumor (continued). "We also found that CD171/L1CAM and mTOR were increased at progression in tumor biopsies from two matched cases of patients receiving targeted therapy with BRAFi." (PMID 33082316, 2020). "The PI3K/AKT/mTOR axis involved in tumor survival, proliferation and distant metastasis and the relevant targeted therapy is under study." (PMID 32023262, 2020). "Further, mTOR pathway activation influences the expression of glycolytic enzymes to induce an increase in glycolysis, eventually promoting tumor cell growth." (PMID 32626538, 2020). "A large number of trials evaluated mTOR inhibitors as modulators to promote anti-tumor immunity and immune cell function." (PMID 32483450, 2020). "Targeting PI3K/AKT/mTOR‐mediated autophagy is important for increasing the chemosensitivity of tumor cells and preventing drug resistance." (PMID 32335998, 2020). "After that, tumor xenografts were used to explore the effect of FKBP4 on NSCLC tumor growth in vivo, and the phosphorylation of Akt and mTOR was measured by western blot." (PMID 33354489, 2020). "Chemotherapy induced a down-regulation of the p-mTOR(Ser2448) in metastases and in non-tumor surrounding tissues in treated patients compared to untreated (P = 0.001 and P = 0.005, respectively)." (PMID 33362215, 2020). "AKT is an important effector of the PI3K/AKT/MTOR signaling pathway and has been considered an oncogene essential for tumor initiation and growth." (PMID 33354218, 2020). "These phosphoproteomics analyses support our initial findings (using dephosphorylated proteins) that subtype-1 tumours display increased mTOR signalling." (PMID 31988390, 2020). "Further studies have confirmed that miR-1 can suppress c-Met/PI3K/Akt/mTOR signaling and impair tumor progression." (PMID 32083078, 2020). "We found PL induces the cell cycle arrest and apoptosis through regulating several downstream effectors of the PI3K/AKT/mTOR signaling pathway to further inhibit the proliferation of tumor cells." (PMID 33117085, 2020). "MiR-21 and miR-106a, by inhibiting PTEN, activate the PI3K/AKT/mTOR pathway, which leads to the induction of the proliferative properties of the tumor cell, as well as to the suppression of apoptosis and autophagy." (PMID 33142817, 2020). "mTOR inhibition was confirmed in the tumours by assessing the expression levels of p‐S6 in P2RY12+ CD49d− TAM‐MG and P2RY12− CD49d+ TAM‐BMDM by flow cytometry." (PMID 32567735, 2020). "Intriguingly, CXCL12/CXCR4 interaction induced mTOR signaling not only influences the immune cells chemotaxis, but also participates in tumor cells migration, such as gastric, pancreatic and renal cancer cells 161-163." (PMID 32483450, 2020). "Tumor cells maintain their amino pools through uptake of exogenous amino acids which is under tight regulation through cellular receptor expression and mechanistic Target of Rapamycin kinase (mTOR)." (PMID 32927667, 2020). "MiR-99a is identified to directly bind to mTOR and functions as a tumor suppressor, modulating radiosensitivity." (PMID 32122355, 2020). "Consistent with PTEN deletion causing an aberrant activation of the mTOR pathway, treatment with the mTOR inhibitor rapamycin induced delayed tumour growth in these models." (PMID 33126717, 2020). "We developed in vitro organoids assay and ex vivo tumor slice drug assays to investigate the effects of mTOR- and CSC-targeting compounds." (PMID 32656088, 2020). "To inhibit the PI3K/AKT/mTOR pathway, we added the mTOR inhibitor everolimus, which further increased anti-tumor activity in cells." (PMID 32927828, 2020). "For hepatocarcinoma, erlotinib induces autophagy through blocking the PI3K/AKT/mTOR pathway to enhance tumor resistance." (PMID 32373608, 2020).
tumor (continued). "Another significant difference between the two groups is the higher frequency of primary tumor resection in the p-mTOR/p-S6K positive group, which seems to correlate with a better survival in retrospective series." (PMID 32397669, 2020). "The antineoplastic activity of mTOR inhibitors is based on interfering with PI3K/AKT/mTOR signaling pathway via inhibiting various proteins that are involved in promoting tumor growth." (PMID 32222803, 2020). "mTOR inhibitors (i.e. Sirolimus and Everolimus) are found to be effective in suppressing the overall disease progression of TSC, through inhibiting the mTOR pathway and anti-tumour effect." (PMID 32988393, 2020). "Thereby, Akt/mTOR signaling pathway plays an important role in a variety of cellular biological processes of tumor cells, including autophagy, proliferation, migration, invasion, and apoptosis." (PMID 33282634, 2020). "Given that a high percentage of OCCC tumours carry mutations which result in hyperactivation of the AKT/mTOR pathway, we examined the ability of an mTOR inhibitor, AZD-8055 to effect cell viability." (PMID 33153119, 2020). "There was a significantly reduced pericyte coverage on CD31+ tumor vessels of mTOR inhibitor-treated tumors." (PMID 32923403, 2020). "Given the importance of mTOR signaling in T cell activation and acquisition of effector functions, the mTOR inhibitor rapamycin is generally viewed as immunosuppressive, and mTOR signaling has indeed been shown to support anti-tumor T cell responses." (PMID 33170123, 2020). "PD-L1 expression on tumor cells has been found to support tumor glycolysis via the activation of mTOR/Akt pathway." (PMID 33324565, 2020). "Here, the authors use the Drosophila accessory gland to model human prostate acini and show that Ras/MAPK and PI3K/AKT/mTOR pathways are co-activated in two autocrine loops by dEGF and dIGF, inducing basal extrusion and subsequent tumour formation." (PMID 32385236, 2020). "This dual PI3K/mTOR inhibitor led to significant changes within the tumour microenvironment by prolonging the time taken for the normalisation of tumour vascularity." (PMID 32443649, 2020). "Previously, we showed that feeding Apc+/Min mice the mTOR (mechanistic target of rapamycin) inhibitor rapamycin reduced their tumor burden to extend their lifespan by >5 times at their median survival." (PMID 31903726, 2020). "The activation of PI3K/AKT/mTOR pathway in tumor cells reduces the pro-apoptotic effect and the cytotoxic effect of chemotherapy drugs, leading to resistance." (PMID 33585182, 2020). "mTOR mediates cell growth and alterations in mTOR pathway have been related to the development of several other neoplasms." (PMID 32961989, 2020). "This literature review identified several studies utilising PI3K, AKT and/or mTOR inhibitors to enhance the radiosensitivity of different types of tumour." (PMID 32443649, 2020). "Previous study has shown that mTOR and eIF4E are two major proto-oncogenes related to oncogenic transformation, which are involved in tumor growth and development." (PMID 32023262, 2020). "Taken together, the silencing of miR-135b promotes the JADE-1 expression, which inactivates the AKT/mTOR pathway and ultimately results in inhibition of self-renewal and tumor growth of PCSCs." (PMID 32351328, 2020). "It has been reported that Everolimus is an mTOR inhibitor that can prevent tumor progression and improve survival in preclinical HCC models." (PMID 32201399, 2020). "Given the substrate preferences of the different ALDH isoforms, it would be interesting to determine if upregulation of the mTOR pathway induced metabolic rewiring in PCa cells, or metabolic diversification of subpopulations within the tumor." (PMID 32656088, 2020). "Further mechanistic studies are needed to link biomarkers with PI3K/Akt/mTOR signaling activity to identify precision targets for therapy, i.e., to identify the ideal targeted inhibitor for an individual tumor." (PMID 33053661, 2020).
tumor (continued). "Endothelial–mesenchymal transition is known to contribute toward tumor progression and metastasis, and thus, the precise role of mTOR inhibitors on endothelial–mesenchymal transition when combined with TRT merits close investigation." (PMID 33037092, 2020). "The PI3K/AKT/mTOR cascade is one of the most crucial signaling in tumor, which controls various cellular activities including cell growth and migration." (PMID 32772918, 2020). "Carcinogenic activation of mTOR is involved in the process required for tumor cell survival, growth, and proliferation." (PMID 33144562, 2020). "At the proteome level, we show that tumours belonging to the less severe subtype are characterised by aberrant mTOR signalling, whereas those belonging to the more severe subtype are characterised by disruptions in SMAD and cell cycle-related processes." (PMID 31988390, 2020). "The Akt/mTOR signaling pathway has been revealed to be overactivated in tumors and involved in tumor progression, including NSCLC." (PMID 32337219, 2020). "Their anti-tumour activity relates to mTOR inhibition by the activation of AMPK and LKB1, thus reducing cellular proliferation." (PMID 33092283, 2020). "This review describes the relationship between the mTOR signaling pathway and tumor cell growth, metabolism, apoptosis and autophagy)." (PMID 32175074, 2020). "For instance, the CRP arrest cell-cycle at the sub G1 phase by negatively regulating the PI3K/AKT/mTOR signaling pathway in myeloid leukemia and tongue squamous cell carcinoma thus promoting tumor progression." (PMID 33013829, 2020). "This highlights the significance for mTOR inhibitors to be designed to diffuse beyond the outer layers of tumours in a reasonable time." (PMID 33142217, 2020). "Palbociclib with PI3K/mTOR inhibitor PF-05212384 in patients with estrogen receptor positive (ER+) metastatic breast cancer reported promising preliminary anti-tumor activity with manageable toxicities." (PMID 32899250, 2020). "Consistent with our in vitro data, we also observed enhanced levels of phospho-S6, an indicator of activated mTOR signaling, in the M2BPGi-treated xenograft tumours relative to the controls." (PMID 32624579, 2020). "These tumor tissues showed downregulation of several stem cell markers, Shh and mTOR proteins as well as upregulation of pro-apoptotic (BAX/CAS3/CAS8) genes." (PMID 32575925, 2020). "We determined that miR-20b and miR-451a directly regulate genes involved in the PI3K/AKT/mTOR signaling pathway, and modification of their expression had a tumor-suppressive role in GC." (PMID 32013265, 2020). "The metabolisms of tumor cells can be regulated by the mTOR pathway to meet their proliferative and nutritional needs." (PMID 32175074, 2020). "Inhibition of mTOR promotes the expansion of immunosuppressive Tregs that can strengthen the effect of anti-tumor immune responses in ccRCC." (PMID 33665156, 2020). "In particular, the inhibitor of the mammalian target of rapamycin (mTOR), everolimus, is recommended by the European Neuroendocrine Tumor Society (ENETS) guidelines for progressive, G1/G2 PAN-NETs." (PMID 32748870, 2020). "Regarding prevention of HCC recurrence, several retrospective single-center studies, further meta-analyzed, have reported reduced tumor recurrence rates in patients receiving mTOR inhibitors-based immunosuppression." (PMID 32070029, 2020). "Together, these data indicate that compound 6 treatment leads to inhibition of the mTOR pathway only in glucose-starved cells, as was the case with other compounds identified previously to selectively kill tumor cells under glucose starvation." (PMID 32033217, 2020).
tumor (continued). "It is hoped that the action mechanisms of the mTOR signaling pathway can be clearly studied in the future, and then selective mTOR inhibitors can be developed to improve anti-tumor activity and reduce side effects." (PMID 32175074, 2020). "From several drugs tested, mTOR inhibitors showed a great efficacy in stopping tumor cell growth in our cell lines." (PMID 32373532, 2020). "mTOR is hyperactivated in a large number of tumor types, and among them, in many hematologic malignancies." (PMID 32053876, 2020). "In liver cancer, the PI3K/PTEN/Akt/mTOR pathway activated is involved in tumor invasion and metastasis by up-regulating matrix metallopeptidase 9 (MMP-9)." (PMID 32175074, 2020). "We observed that subtype-1 tumours were characterised by alterations of the mTOR signalling pathway, and the expression levels of different mTOR pathway proteins were positively correlated to each other." (PMID 31988390, 2020). "Neu2-overexpressed tumors showed reduction in tumor mass with downregulation of stem cell markers/Shh/mTOR and upregulation of Bax/Caspase8/Caspase3." (PMID 32575925, 2020). "Tumor suppressor metformin (MF) can also inhibit AKT/mTOR pathway by activating AMPK, which implied that MF treatment obviously relied on miR-21 expression." (PMID 33344224, 2020). "Our results indicate that TTK regulates the proliferation and apoptosis of tumor cells through Akt‐mTOR signaling pathway." (PMID 32530571, 2020). "This study demonstrated that the knockdown of lncRNA cancer susceptibility candidate 9 (CASC9) suppressed tumor progression by inhibiting the proliferation of OSCC cells and promoting autophagy-mediated cell apoptosis via the modulation of AKT/mTOR pathway." (PMID 32384682, 2020). "In summary, these data indicate that combined treatment with AKT and mTOR inhibitors is effective on MPNST cells in vitro but tumour resistance can occur rapidly in vivo by restoration of AKT/mTOR signalling." (PMID 32102484, 2020). "This indicated that TPT1-induced tumor progression is at least partially attributable to its suppressive effect on mTOR-dependent autophagy." (PMID 32792860, 2020). "Three main pathways are upregulated in HCC due to a metabolic switch and elevated ROS production: glycolysis, MAPK pathway, and PI3K/AKT/mTOR pathway, which can interact with one another to increase their effects in tumor proliferation and survival." (PMID 32585931, 2020). "In our work, patients with a p-mTOR/p-S6K positive tumor seem to have a better PFS and OS as compared to those with p-mTOR/p-S6K negative tumor." (PMID 32397669, 2020). "LncRNA cancer susceptibility candidate 9 (CASC9) suppresses autophagic cell death via the AKT/mTOR signaling and cell proliferation and tumor progression in oral squamous cell carcinoma." (PMID 33239065, 2020). "The purpose of this review is to elucidate the relationship between mTOR signaling pathway and tumor development and to introduce the research progress of mTOR inhibitors." (PMID 32175074, 2020). "As expected, western blot verified that inactivation of SNHG3 distinctly led to the elevation of phosphorylated AKT, mTOR and ERK, indicating that SNHG3-silencing triggered tumor progression in PTC by modulating AKT/mTOR/ERK signaling pathway." (PMID 32284745, 2020). "Another mTOR inhibitor decreased survival and invasion of colorectal CSCs in vitro, and suppressed tumor growth in vivo." (PMID 32626705, 2020). "Here, we found that in subtype-1 tumours various phosphoproteins that participant in mTOR signalling – such as MTOR-pS2448, GSKB-pS21-S9, PDK-pS241 and growth factor receptors EGFR-pY1068 and ERBB-pY1248 – all exhibited increased phosphorylation 32,33." (PMID 31988390, 2020). "Recent studies showed that the down-regulation of miR-144 via mTOR upregulation leads to tumor progression." (PMID 32276343, 2020).
tumor (continued). "The inhibition of the mTOR pathway by currently available pharmacological compounds (i.e., sirolimus or everolimus) is able to hamper tumor progression both in vitro and in animal models." (PMID 32070029, 2020). "It has been shown that incubating UMUC3 cells with increasing concentrations of the mTOR-inhibitor, temsirolimus, over six months does result in resistance, exhibited by reactivated tumor growth and proliferation with mTOR and mTOR-related protein activation." (PMID 32759798, 2020). "mTOR is a crucial activator of the PI3K/Akt pathway, and targeting mTOR has been reported as an effective approach to suppress tumor progression." (PMID 32645691, 2020). "As a key effector molecule of PI3K/AKT/mTOR, RICTOR plays an important role in tumorigenesis and invasion and causes tumor resistance to RTK-TKIs by AKT-dependent and -independent pathways, which seriously limits patients’ benefits from targeted drugs." (PMID 32041519, 2020). "In combination with the previous finding that down-regulation of MUC1 would inhibit drug resistance in tumor cells, our data indicated that the level of MUC1 was critical in determining the efficiency of anti-tumor drugs targeting PI3K/Akt/mTOR signaling axis." (PMID 33375426, 2020). "And the overexpression of miR-1271 in vitro cell experiments will significantly inhibit the expression of mTOR, then decrease the drug resistance of tumor cells." (PMID 32792861, 2020). "The activity of AKT and mTOR is crucial for the malignant behaviour of NF1-associated neoplasms such as MPNST or optic pathway gliomas, as well as for other tumour entities such as hepatocellular carcinoma and cholangiocarcinoma." (PMID 32102484, 2020). "mTOR is an atypical serine/threonine kinase which can promote tumor development by regulating cell biological processes such as metabolism, autophagy, and cellular stress." (PMID 33354489, 2020). "Combinatorial treatments targeting both MAPK pathway and PI3K/AKT/mTOR pathway have been proposed to block tumor proliferation and promoting cellular apoptosis." (PMID 32585931, 2020). "The levels of phospho-Akt (p-Akt), phosphor-mTOR (p-mTOR), and phospho-p70S6 (p-p70S6), all of which are mTOR substrates, were measured in the two tumor cell lines." (PMID 32466612, 2020). "This is in agreement with increased mTOR activity in AITL-like tumor Tfh cells found in the two above studies since FoxO1 is a negative regulator of mTORc1." (PMID 32796826, 2020). "Further immunohistochemical analysis showed that in late stage spinal metastases, the proliferation of tumor cells was slightly lowered after mTOR inhibition, detected by a decrease in the Ki67 labeling index." (PMID 32140451, 2020). "Herein, the HNK and DSF/Cu codelivery liposome system modified with DCDX peptide was designed to treat GBM via regulating mTOR pathway for remodeling tumor metabolism and TIME." (PMID 32817393, 2020). "We next employed H1975 and U87MG in vivo tumor models to study mTOR inhibitor effects on TF expression and function." (PMID 32923403, 2020). "The lack of efficacy of mTOR targeting has been ascribed to the development of tumor cell resistance, forcing the activation of compensatory signaling pathways that dampen the potential of mTOR inhibitors." (PMID 32512849, 2020). "Taking advantage of transcriptomic data from TAM‐MG and TAM‐BMDM isolated from GL261 tumours, deregulation of the mTOR pathway was further investigated in these two cell populations." (PMID 32567735, 2020). "The PI3K/AKT/mTOR signaling pathway is an essential component of the glycolysis in tumor cells; it upregulates HIF-1α and then increases the LDHA expression, thus shifting metabolism to aerobic glycolysis." (PMID 32076440, 2020). "The PI3K/AKT/mTOR pathway is related to the regulation of tumor cell apoptosis, tumor aggressiveness and a worse prognosis." (PMID 33316872, 2020).